S100A9 (S100 calcium binding protein A9)
Diseases named in the same sentence as S100A9 in open-access papers (continued):
Sharing a sentence is not in itself a finding about the gene and the disease.
colitis (continued). "For example, prophylactic treatment with an S100A9 inhibitor has been shown to reduce colitis-induced neuroinflammation and NLRP3−/− mice showed attenuated neuroinflammation and neurological dysfunction following DSS." (PMID 39021817, 2024). "Reduced colitis severity was also reflected in differential tissue mRNA expression: mucosal transcript levels of S100a9, Il1b and Ptgs2 were significantly reduced in DSS-induced colitis when calcineurin inhibitors were applied." (PMID 37358998, 2023). "Increased accumulation of CD11B+Ly6G+S100A9+ neutrophils in colon lamina propria in Il17b-/- colitis mice were validated by flow cytometry." (PMID 36814913, 2023). "We identified CD11B+S100A9+ cells in colon tissue of DSS-induced colitis mice and they exclusively expressed in neutrophils (CD11B+Ly6Ghigh cells)." (PMID 36814913, 2023). "Though S100A9 and Lcn2 are upregulated in colitis, this is the first study to observe evidence of these proteins in the brain of mice with colitis." (PMID 34983592, 2022). "LFD 2% male mice had higher expression of Acod1, Lcn2, and S100a9, which are upregulated in colitis and inflammatory bowel disease." (PMID 36501176, 2022). "Other groups have previously demonstrated that S100A9 and Lcn2 are upregulated in the colon of mice with colitis." (PMID 34758843, 2021). "Our results demonstrate that anemoside B4 prevents TNBS-induced colitis by inhibiting the NF-κB signaling pathway through deactivating S100A9, suggesting that anemoside B4 is a promising therapeutic candidate for colitis." (PMID 33461587, 2021). "Our data demonstrate a significant increase in the inflammatory chemokine, KC, as well as inflammatory biomarkers, S100A8 and S100A9, in the colons, serum and brains of mice with colitis." (PMID 34758843, 2021). "S100A9 is highly expressed during the acute phase of colitis; however, it is down-regulated by colonic chitinase-3-like 1 (CHI3L1), a pseudo-chitinase that is upregulated during the chronic phase of colitis." (PMID 34572138, 2021). "In summary, our study demonstrated that anemoside B4 exhibited significant protective effects on TNBS-induced colitis via suppressing the S100A9/MAPK/NF-κB signaling pathway and inhibited neutrophil recruitment and activation." (PMID 33461587, 2021). "Pharmacological inhibition of S100A9, one of the transcripts identified by RNA sequencing, attenuated colitis severity and systemic and neuroinflammation." (PMID 34758843, 2021). "It is found that S100A9, is highly expressed in G‐MDSC‐derived exosomes, and its blockade suppresses CRC cell stemness and the susceptibility of mice to AOM/DSS‐induced colitis‐associated colon cancer." (PMID 31559140, 2019). "The proinflammatory S1008 and S100A9 proteins were reported to regulate MDSC accumulation in all regions of dysplasia and adenoma in a colitis-associated colon cancer model." (PMID 31620141, 2019). "We discovered that the area of colon ILF was shrunk significantly in neutralizing S100a9 Ab-treated colitis mice." (PMID 29326691, 2017). "In this study, we demonstrated for the first time that neutralizing S100a9 antibody is effective in ameliorating DSS-induced colitis and AOM/DSS-induced CAC." (PMID 29326691, 2017). "The protective effects of anti-S100a9 Ab on chemically induced colitis and CAC are related to the inhibition of the inflammatory responses and pathways that links colitis to colon cancer." (PMID 29326691, 2017). "In this study, we have tried to clarify the role of a neutralizing S100a9 antibody in the development of colitis and CAC." (PMID 29326691, 2017). "We observed that blockade of S100a9 significantly ameliorated DSS-induced colitis and AOM/DSS-induced CAC in mice." (PMID 29326691, 2017). "The colitis mice given a neutralizing S100a9 antibody produced less inflammatory cytokines, such as Tnfα, Il1β, Il6, Il17a, Ifnγ, and Il12a, all of them are master regulators of inflammation and tumorigenesis." (PMID 29326691, 2017).
colitis (continued). "Infiltration of inflammatory cells into the colon is a character of DSS colitis, and our study showed that blocking S100a9 inhibited the recruitment of innate immune cells, including macrophages, neutrophils, and DCs in the colons." (PMID 29326691, 2017). "Dextran sulfate sodium-induced colitis is characterized by the infiltration of inflammatory cells into the colon, we thus analyzed the effect of anti-S100a9 Ab treatment on the recruitment of innate immune cells." (PMID 29326691, 2017). "Increased transcription of AMP transcripts, such as S100a8, S100a9, S100a14 and lactoferrin (Ltf) in the lumen of the gut during colitis suggests a required ability for commensal microbes to withstand antimicrobial activity during inflammation." (PMID 27003245, 2016). "Consistent with antimicrobial activity in the lumen of the gut during colitis, we observed significantly higher expression of the AMPs S100a8, S100a9, S100a14 and Ltf as well as Nos2 in colon contents." (PMID 27003245, 2016). "In contrast, S100A9 expression was highly induced during the course of acute DSS-induced colitis in WT mice, but dropped significantly during the chronic phase of colitis." (PMID 26431492, 2015). "In the present study, we found increased IL-6 expression in CECs from mice with DSS-induced colitis and demonstrated directly that IL-6 induced S100A9 expression in both CECs from mice with colitis and in a human IEC cell line." (PMID 22962574, 2012). "In gastrointestinal epithelial cells, their expression is induced during inflammation and increased protein expression of S100A9 has been detected in colitis-related carcinogenesis in mice." (PMID 22509329, 2012). "We demonstrated a novel mechanism in which IL-6 increases S100A9 levels via STAT3 activation in CECs in an experimental murine model of DSS-induced colitis." (PMID 22962574, 2012). "The effects of soluble gp130-Fc protein (sgp130Fc) and S100A9 small interfering (si) RNA (si-S100A9) on DSS-induced colitis were evaluated." (PMID 22962574, 2012). "In contrast, our results suggest that ECs can also trigger inflammatory responses by secreting S100A9 in mice with colitis." (PMID 22962574, 2012). "Consequently, peptides and antibodies that specifically target S100A9 in the colon have shown efficacy in mouse models, reducing both colitis and CAC by inhibiting their interactions with TLR4 and RAGE." (PMID 40565156, 2025). "Moreover, the anti-inflammatory effects of tasquinimod and hederacoside C were demonstrated by their ability to alleviate colitis, primarily through the inhibition of S100A9 release from MØ in mice and neutrophils in a rat colitis model, respectively." (PMID 40565156, 2025). "Specifically, S100A9 is significantly overexpressed in mice with colitis." (PMID 38448514, 2024). "Inhibition of S100A9 by a neutralizing anti-S100A9 antibody can reduce the colitis severity." (PMID 36814913, 2023). "Whilst S100A8 and S100A9 may play a central role in propagating neuroinflammation in colitis models, it has been suggested that NLR family pyrin domain containing 3 (NLRP3) protein activation may be involved." (PMID 34983592, 2022). "Furthermore, we revealed that anemoside B4 prevented colitis in rats by inhibiting the NF-κB signaling pathway through inactivating S100A9." (PMID 33461587, 2021). "Because we detected S100A8/A9 upregulation in the serum and brains in mice with colitis, we hypothesized that inhibition of S100A9-signaling would reduce the neuroinflammatory signature in mice with colitis." (PMID 34758843, 2021). "In humans, however, drugs that target S100A9 could be given after colitis onset as soon as patients become symptomatic." (PMID 34758843, 2021). "Similarly, treatment with Paquinimod, an inhibitor of S100a9, can also rescue colitis severity of Dok3−/− mice." (PMID 34743196, 2021).
colitis (continued). "In the colitis-associated cancer mouse model, colonic chitinase 3-like 1 (CHI3 L1) can bind to RAGE, and thus disrupt the S100A9-associated expression positive feedback loop during early immune activation, creating a S100A9 low colonic environment, especially in the later phase of colitis." (PMID 29942307, 2018). "In conclusion, treatment of mice with anti-S100a9 antibody during colitis and CAC development exerted a protective effect on intestinal inflammation and tumorigenesis, suggesting that the neutralizing S100a9 antibody is a potential therapeutic agent for treating human IBD." (PMID 29326691, 2017). "In this study, anti-S100a9 Ab acquired similar therapeutic efficacy in DSS-induced colitis mice." (PMID 29326691, 2017). "This CHI3L1-mediated cell proliferation/survival involves partial downregulation of the pro-apoptotic S100A9 protein that is highly expressed during the acute phase of colitis, by binding to the S100A9 receptor, RAGE (Receptor for Advanced Glycation End products)." (PMID 26431492, 2015). "However, the S100A9 level in Brp39KO mice was significantly higher as compared to WT during the chronic phase of colitis." (PMID 26431492, 2015). "The infiltration of GR-1+ cells and histopathology of colon tissue were consistently and notably reduced when S100A9 expression was down-regulated, suggesting that the recruitment of immune cells in the colonic epithelium results from IL-6-induced S100A9 expression in CECs in DSS-induced colitis." (PMID 22962574, 2012). "We investigated the role of IL-6 in S100A9 expression in CECs using a colitis model." (PMID 22962574, 2012). "To further confirm whether these findings result from S100A9 expression in CECs from mice with DSS-induced colitis, we suppressed S100A9 expression by si-S100A9/CH-NP injection." (PMID 22962574, 2012). "Elevated S100A9 expression in CECs mediated by an IL-6/STAT3 signaling cascade may play an important role in the development of colitis." (PMID 22962574, 2012). "Lastly, we explored the effects of S100A9 protein in CECs on DSS-induced colitis." (PMID 22962574, 2012). "S100A9 expressed in the CECs may contribute to the disease progression of active colitis by recruiting leukocytes within the colonic epithelia, presumably resulting in the breakdown of the epithelial lining and intestinal homeostasis." (PMID 22962574, 2012). "Thus, S100A9 is a good biomarker and therapeutic target for colitis." (PMID 36814913, 2023). "In addition, the interferon-responsive gene Ifitm3 is critical to early colon cancer development, along with S100a9 and Slpi, which, when highly expressed in inflamed colon tissues in mice and patients with colitis and IBD, respectively, can be considered as potent amplifiers of tumor invasion." (PMID 36901742, 2023). "In conclusion, this study found that colitis drives mild to moderate inflammation in the brain and increased inflammatory cytokines in the serum, and that colonic and neuroinflammation were mitigated by prophylactic treatment with the S100A9 inhibitor paquinimod." (PMID 34758843, 2021). "Recent studies have revealed elevated levels of S100A9 in the peripheral blood mononuclear cells (PBMCs) of patients with IBD and the serum of experimental colitis rats compared to that in controls." (PMID 40565156, 2025). "In murine colitis and CAC models, elevated serum concentrations of S100A8 and S100A9 were detected, in addition to notable enhancements in their interaction with PRRs, especially TLR4, and RAGE." (PMID 38892354, 2024). "In colitis, CD11B+S100A9+ neutrophils were significantly increased in WT mice compared to mice without DSS treatment, and this population was 2-fold increase in Il17b-/- colitic mice." (PMID 36814913, 2023). "The expression of S100a9, S100a8, Lcn2, Il1f9, Mmp8, and Mmp9 were significantly increased in CD45+ cells from Il17b-/- colitis mice (P < 0.05)." (PMID 36814913, 2023).
colitis (continued). "During colitis, neutrophils abundantly express and secrete S100A8 protein, which forms an S100A8/S100A9 heterodimer (also called calprotectin; a non-invasive biomarker in IBD)." (PMID 37006281, 2023). "First, we treated Il17b-/- colitis mice with recombinant mouse IL17B and detected cell response in colon with flow cytometry and found that IL17B treatment can inhibit S100a9+ neutrophils infiltration in colon tissue." (PMID 36814913, 2023). "Of note, host antimicrobial gene expression levels (Lcn2, S100a8, S100a9) were similarly upregulated in all DSS-treated mice, and all DSS-treated mice developed similar levels of colitis, as shown by histopathology evaluation of the distal colon." (PMID 34853318, 2021). "We confirmed upregulation of Lcn2 and S100A9 transcripts and measured increased Lcn2 and S100A8/A9 protein expression in brains isolated from mice with colitis, albeit expression is markedly less than the levels detected in mice injected with LPS." (PMID 34758843, 2021). "Thus, S100a9 may be a therapeutic target for colitis and CAC." (PMID 29326691, 2017). "We generated a mouse model of experimental colitis induced by dextran sulfate sodium (DSS) and showed that IL-6 triggered S100A9 production in CECs, which was mediated through STAT3 activation." (PMID 22962574, 2012). "sgp130Fc or si-S100A9 administration to DSS-treated mice reduced granulocyte infiltration in CECs and induced the down-regulation of S100A9 and colitis disease activity." (PMID 22962574, 2012). "In a recently published study, DSS-induced colitis found upregulation of inflammatory-related proteins S100A8, S100A9 (also known as myeloid related protein (MRP) 8 and MRP14), and lipocalin-2 (Lcn2, also known as neutrophil gelatinase-associated lipocalin) in the brain." (PMID 34983592, 2022). "Our results showed that blocking S100a9 protein by neutralizing antibody effectively inhibited not only DSS-induced colitis but also AOM/DSS-induced CAC in mouse model." (PMID 29326691, 2017). "In addition, our in vivo and in vitro results demonstrated that expression of CHI3L1 and S100A9 are inversely correlated in acute- and chronic-DSS-induced colitis in WT and Brp39 KO mice." (PMID 26431492, 2015). "Conversely, in the Brp39 KO mice, Annexin V levels were increased during the transitional phases in the course of colitis, presumably a result of imbalance between high S100A9 and no CHI3L1 expression levels." (PMID 26431492, 2015). "The expression levels of S100A9 mRNA were notably suppressed in the group of mice treated with si-STAT3/CH-NPs, resulting that STAT3 regulated the expression level of S100A9 in the CECs in DSS-induced colitis." (PMID 22962574, 2012). "IL-6 and S100A9 expression, signal transducer and activator of transcription 3 (STAT3) phosphorylation, and infiltration of immune cells were analyzed in mice with dextran sulfate sodium (DSS)-induced colitis." (PMID 22962574, 2012). "In DSS-induced colitis, numerous S100a9-positive cells (a marker of inflammation) infiltrated into the mucosa and epithelial layer of the damaged colon, while no infiltration by S100a9-positive cells was observed in the colons of mice treated with RI-962." (PMID 36371441, 2022). "As expected, colitis induced by CD4+CD45RBhigh T cells in immune-depleted mice was associated with a significant increase in Th17 genes, IFNG, IL10 as well as S100A8 and S100A9 (data not shown)." (PMID 30405600, 2018). "In view of the protective effect of neutralizing anti-S100a9 antibody against DSS-induced colitis and AOM/DSS-induced CAC in mouse model, this study suggests that anti-S100a9 antibody may provide a novel therapeutic approach to treat ulcerative colitis and may decrease the risk for developing CAC." (PMID 29326691, 2017). "However, the function of neutralizing S100a9 antibody in colitis and CAC has not been well studied, and the mechanism is unclear." (PMID 29326691, 2017).
colitis (continued). "Our observations are consistent with a previous report that showed S100A9 is an early responder expressed during the initial stage of acute colitis within the first two weeks of initiation but is absent during the chronic phase of colitis." (PMID 26431492, 2015).
diabetes (34 papers, 2006 to 2025). "There are several studies reported S100A9 blockage promoting the improvement in diabetic associated diseases, such as diabetic nephropathy, microcalcification and chronic wounds in diabetes mice." (PMID 40384874, 2025). "Urinary exosomes containing S100 calcium-binding protein A9 were found to be significantly increased in pregnant women with diabetes mellitus, with high risk for developing PE." (PMID 41155408, 2025). "Recent research indicates that high levels of plasma S100A9 are associated with various diseases such as diabetes, myocardial infarction, systemic lupus erythematosus, and ischemic stroke." (PMID 39107960, 2024). "In line with their pleiotropic functions, S100A8 and S100A9 have been implicated in a variety of diseases, ranging from arthritis to diabetes and cardiovascular diseases." (PMID 35998224, 2022). "The serum levels of S100A12 in RA patients in MLR analysis were positively associated with ACPA, a history of diabetes, and serum levels of S100A9 (P < 0.05)." (PMID 19284577, 2009). "S100A12 levels were associated with presence of ACPA, history of diabetes, and serum S100A9 levels." (PMID 19284577, 2009). "The heterodimeric S100A8/S100A9 might therefore play a hitherto unknown role in triggering atherosclerosis in diabetes and renal failure, pathophysiological entities associated with a high AGE burden." (PMID 16573830, 2006). "Additionally, diabetes was associated with S100A9 serum concentration (p=0.025)." (PMID 31632476, 2019). "The emergence of matrix metalloproteinases (e.g., MMP2) and S100A9 in diabetes and steatosis prediction models further supports the role of adiposome-mediated remodeling and inflammatory signaling in these diseases." (PMID 40981199, 2025). "The molecular bases of S100A9-mediated mitochondrial dysfunction and its wider significance in diabetes complications should be further investigated in future studies." (PMID 40384874, 2025). "S100A9 blocking by paquinimod or macrophage depletion (clodronate) alleviated diabetes-induced cardiac dysfunction, inflammatory macrophage infiltration, serum pro-inflammatory cytokines." (PMID 40384874, 2025). "The dual actions of S100A9 in mediating cachexia and diabetes underscore its important roles in PC and potential implications in detection and therapy." (PMID 37280516, 2023). "Gal-3 and S100A9 represent potential targets for therapeutic interventions to prevent or manage diabetes in the context of pancreatic cancer." (PMID 37915694, 2023). "Of note, the slight increase in plasmatic S100A9 level observed in poorly controlled subjects with diabetes is also recapitulated in our ID mouse model." (PMID 35840613, 2022). "To further evaluate the translational significance of our findings, we performed an observational clinical study aimed at gathering plasmatic S100A9 content in patients with decompensated diabetes and healthy controls." (PMID 35840613, 2022). "Our results are in agreement to previous studies reporting higher levels of S100A9 in saliva of diabetic human adults and children, in which S100A9 were proposed as a predictive factor for diabetes-related microvascular complications." (PMID 33271797, 2020). "Though the mechanism of S100A9 upregulation in diabetes/obesity and its clinical significance needs to be established, other recent studies have demonstrated S100A9 upregulation in diabetes or obesity, further supporting our finding." (PMID 31448371, 2016). "High circulating levels of S100A9 have been identified in patients with cardiovascular disease and diabetes." (PMID 25993652, 2015). "In simple linear regression analysis, the serum levels of S100A12 in RA patients were positively associated with ACPA, RF, history of diabetes, and serum levels of S100A8 and S100A9 (P < 0.05)." (PMID 19284577, 2009). "Diabetes mellitus/hyperglycemia might confer radioresistance via RAGE activation—potentially independently of S100A9." (PMID 40522460, 2025).